PIK3CA (phosphatidylinositol-4,5-bisphosphate 3-kinase catalytic subunit alpha)
Diseases named in the same sentence as PIK3CA in open-access papers (continued):
Sharing a sentence is not in itself a finding about the gene and the disease.
tumor (continued). "Due to observing dramatically different Trastuzumab anti-tumor responses within two xenograft models with the same HER-2 level (2+), but differing PIK3CA mutation status, we sought to determine the AKT pathway activation states within tumor lysates from these models." (PMID 22935382, 2012). "Mutations of PIK3CA, may coexist with either KRAS or BRAF within the same tumor, but KRAS and BRAF mutations appear to be mutually exclusive." (PMID 22586484, 2012). "Together these results indicate that Src interacts with the PI3K pathway to promote tumor growth in PIK3CA mutant tumors and that a subset of patients with this genetic alteration may show benefit saracatinib monotherapy." (PMID 23342270, 2012). "Preliminary results show that a combined test for mutation of FGFR3, PIK3CA and RAS could potentially detect 75% of primary tumours, including 88% of the pTa-T1G1-2 tumours but only 36% of the high-grade and -stage malignancies." (PMID 22899908, 2012). "Likewise either mutation of PIK3CA or silencing of PTEN and subsequent activation of Akt is a frequent form of oncogene addiction in many tumor types." (PMID 23006971, 2012). "PIK3CA and PTEN mutations were detected in 17% and 26% tumours, respectively." (PMID 22454081, 2012). "Across tumor types, we demonstrated a higher prevalence of RAS (KRAS, NRAS) or BRAF mutations (47%) and KRAS mutations (38%) in patients with mutant PIK3CA compared to those with wtPIK3CA (mutant RAS or BRAF present in 24%, p = 0.001; mutant KRAS present in 16%, p = 0.001)." (PMID 21829508, 2011). "The role of PIK3CA in tumor cell proliferation is well-studied as compared to its role in invasion." (PMID 22064833, 2011). "However, at the time, very little is known about the interrelationship between TILs, MSI, and other tumour molecular features, such as the CpG island methylator phenotype (CIMP), global DNA hypomethylation, and KRAS, BRAF, and PIK3CA mutations." (PMID 22110523, 2011). "Although our results were obtained in a relatively small, single arm study, gefitinib-treated patients whose tumours contained low CEN7/cell (or low EGFR/CEN7 gain or low EGFR gain), high PTEN loss, and high PIK3CA gain had significantly shorter PFS and OS than other patients." (PMID 22095222, 2011). "However, little is known about the interrelationship between tumor-infiltrating T cells, MSI, and other molecular features of CRC, including CIMP, global DNA hypomethylation, or KRAS, BRAF and PIK3CA mutations." (PMID 24212797, 2011). "We detected a similarly substantial overlapping between the KRAS and PIK3CA mutations, but all PIK3CA mutated tumours in the present study were non-responders." (PMID 21439039, 2011). "In order to assess any relationship between oncogenic activation or loss of tumour suppressor function in the PI3K/AKT and MAPK/ERK signalling pathways, mutations in PIK3CA, PTEN, BRAF and K-RAS, as well as loss of PTEN expression, were tested in relation to each other." (PMID 21473780, 2011). "During tumor growth, PIK3CA may be expressed at low levels and p110α localizes mainly to the cytoplasm in cancer cells proliferating in proximity to vessels in a metabolically lush microenvironment." (PMID 18335034, 2008).
tumor (continued). "Furthermore, PIK3CA mRNA over-expression positively correlated with increased proliferation and decreased apoptosis of tumor cells in vivo." (PMID 19384426, 2007). "However, the pre-specified subgroup analysis based on PIK3CA mutation status identified via tumor tissue did not demonstrate a statistically significant difference in PFS (p = 0.1514)." (PMID 40535135, 2025). "The PIK3CA gene has a significant increase in mutation frequency (14.20%) and amplification frequency (5.06%) in GC cell, and its genetic alteration can positively regulate PI3K activity to inhibit autophagy, which is closely associated with tumor progression, disease prognosis and drug resistance." (PMID 40066330, 2025). "Additionally, our findings indicate that mutation frequencies, such as those of PIK3CA and PTEN, may be underestimated due to the non‐specificity of the regions examined (in our case these were present in very specific regions of the tumour such as IF, etc.)." (PMID 40302146, 2025). "Moreover, PIK3CA altered tumours that have been rendered resistant to PI3Kα inhibition through loss of PTEN show lack of FOXM1 downregulation, suggesting FOXM1 may play a role in limiting the efficacy of agents targeting the PI3K-AKT pathway." (PMID 40263319, 2025). "Moreover, it suggests that reducing (rather than ablating) expression of PTEN may affect the response of PIK3CA altered ER+ BC PDX tumour models to PI3Kα signalling inhibition." (PMID 40263319, 2025). "Conversely, gene panels remain the predominant method for the detection of somatic driver mutations in tumor tissue, alongside WES in some institutions, given their high coverage of exonic regions where the majority of actionable alterations reside (e.g., EGFR, BRAF, PIK3CA, KRAS, BRCA1/2)." (PMID 41228293, 2025). "Our study assesses the prognostic value of PIK3CA and ESR1 mutations in DNA derived from extracellular vesicles (EV-DNA) in longitudinal plasma from 59 HR+/HER2-mBC patients previously exposed to aromatase inhibitors, with a comparative analysis against circulating tumor DNA (ctDNA)." (PMID 39684756, 2024). "Moreover, we identified a negative association with PIK3CA mutations, suggesting distinct tumor clusters with activation of alternative pathways." (PMID 39191994, 2024). "In addition to canonical and non-canonical mutations, amplification of the PIK3CA gene has been found in various tumour types." (PMID 38787171, 2024). "Secondly, the function and mechanism of PIK3CA gene mutations have not been fully revealed, especially in terms of their interaction and synergistic effects with other molecular alterations, as well as their relationship with the tumor microenvironment." (PMID 39555098, 2024). "We selected two additional tumor models, T11‐UV and T11‐Apobec, that displayed a high expression of Tgfb1 (both tumor models) and Tgfb2 (T11‐UV), high expression of Vimentin (Vim) and fibrotic marker (Pik3ca), and low expression of Cd36 and apoptosis regulator Bcl2." (PMID 39553439, 2024). "While a previous study found that high PIK3CA copy number gain in HNSCC tumor samples was significantly associated with lower disease-specific survival and larger tumor volume, no studies have been found to date examining the prognostic value of PIK3CA mutations in the ctDNA of HNSCC patients." (PMID 39335101, 2024).
tumor (continued). "For instance, the H1047R mutation in the oncogenic PIK3CA gene in breast cancer enhances PI3K enzyme activity, activating the AKT/mTOR signalling pathway and inducing the glycosylation of membrane metalloendopeptidase, ultimately resulting in tumour cell senescence." (PMID 39270064, 2024). "In addition, PIK3CA and TERT gene mutations have also been detected in some RGNT cases, and these mutations are closely associated with the biological behavior of the tumor and the potential risk of malignant transformation." (PMID 39457636, 2024). "Moreover, having established the link between PIK3CA mutations and TNBC subtypes and the epigenetic profile, we now shift our focus to the specific molecular mechanisms by which PIK3CA orchestrates a tumor cell's propensity for tropism, including its impact on migration and invasion." (PMID 39369580, 2024). "Furthermore, responses were observed regardless of RAS or PIK3CA mutational status and tumor mutational burden levels." (PMID 39062065, 2024). "Moreover, breast cancers with homologs recombination deficiencies (HRD) are characterized by a higher tumor mutational burden, PD-L1 expression, and PIK3CA pathway alteration rate in comparison to ones without HRD." (PMID 37298642, 2023). "A study on the use of BYL719 in combination with paclitaxel to treat HER2− metastatic breast cancer found that patients with tumor/ctDNA mutations experienced better PFS when compared with patients without PIK3CA mutations, and that PFS was also higher in patients with normal metabolism." (PMID 36671478, 2023). "The direction of change was more commonly observed from PIK3CA mutated to wild-type status (14.9%, 95% CI 11.8–18.2; n studies = 24, n tumor pairs = 453; I2 = 35.3%) rather than from PIK3CA wild-type to mutated status (8.9%, 95% CI 6.1–12.1; n studies = 24; n tumor pairs = 943; I2 = 56.4%)." (PMID 37392328, 2023). "According to this study, synchronous ARID1A loss and PIK3CA overactivation synergistically induced upregulation of IL-6, a cytokine that triggers and is triggered by the JAK/STAT pathway, thereby initiating a signaling cycle that promotes tumor cell growth and differentiation." (PMID 37627318, 2023). "Many of the most frequent actionable alterations within TMB-H tumors were within tumor suppressor pathways (PIK3CA/PTEN, CDKN2A, BRCA1/2, NF1, ATM, and TSC1/2), suggesting that many variants may be passenger rather than driver alterations in the setting of highly altered tumors." (PMID 36602798, 2023). "Besides, it is well established that specific oncogenic events in different mammary cell populations lead to dissimilar tumor outcome, as has been shown for the PIK3CA H1047R oncogene that induces distinctive tumors depending on the cellular origin in which the oncogene is expressed." (PMID 36808257, 2023).
tumor (continued). "However, a pooled analysis of two trials evaluating the combined biomarkers of KRAS, NRAS, BRAF, and PIK3CA showed a significantly reduced benefit from anti-EGFR therapy in patients with any mutant tumor compared with patients with all wt tumors (interaction tests P < 0.05 for PFS, OS, and ORR)." (PMID 37974093, 2023). "Furthermore, in the C57BL/6 × 129 Sv background, we had previously reported a tendency to develop tumours by the HTVI of either PIK3CA E545K or H1047R alone, which had similarly conflicted with earlier reports, that these alterations would not elicit carcinogenesis in an FVB/N genetic background." (PMID 37946160, 2023). "Most of the discordance was due to PIK3CA mutations detected in tumor tissue but not in ctDNA." (PMID 37511178, 2023). "Therefore, the retesting of tumor tissue is recommended for patients with no PIK3CA mutations found in their ctDNA." (PMID 38068930, 2023). "Mutations in genes such as PIK3CA, phosphatase and tension homologues (PTEN), AKT1, and tuberous sclerosis 1/2 (TSC1/2) can all lead to dysregulation of signalling pathways, which can drive important physiological processes such as tumour metabolism, proliferation, angiogenesis, and metastasis." (PMID 37489050, 2023). "Although the ST1799/PBR model has an activating E542K PIK3CA mutation, capivasertib (AKTi) monotherapy could not completely arrest tumor growth." (PMID 37725704, 2023). "Since tumor suppressors of the PIK3 pathway such as PTEN (phosphatase and tensin homolog) were found to be mutated in combined HCC/ICC, we tested four different PI3K inhibitors, three of them inhibit predominantly PIK3CA (BKM120, Wortmannin, and LY294002) and one PIK3CD (CAL-101)." (PMID 36402986, 2022). "Thus, in patients with HER2-positive tumours the impact of PIK3CA-mutations is not clear; at least the effects are small and not significant." (PMID 36279023, 2022). "Overall, E2 levels were significantly positively correlated with tumor enrichment in the hallmark estrogen response pathway (red bars) and with the expression of genes demonstrated to be transcriptionally regulated by ER (BCL2, IGF1R, GATA3, PIK3CA) and ligand-dependent ER (ESR1, XBP1, TFF1)." (PMID 36428742, 2022). "Likewise, in patient #34, the discontinuation sample at +169 days showed the presence of one CTC that did not contain that tumor’s dominant PIK3CA mutation, but instead harbored a hotspot IDH1 mutation (#34, Discontinuation, CTC#: E6)." (PMID 34866317, 2022). "In contrast, fast growing ER-negative and undifferentiated tumours, however, may be derived from different precursor cells and independent of activating PIK3CA-mutations." (PMID 36279023, 2022). "PIK3CA-mutations were significantly more often observed in steroid hormone receptor-positive than in steroid hormone receptor-negative tumours (OR 3.38, 95% CI 2.103-5.438), and in HER2-negative than in HER2-positive tumours (OR=2.25, 95% CI 1.451-3.501), respectively." (PMID 36279023, 2022). "The xenograft SJRHB000026 (HRAS G13R, PIK3CA missense mutation) had less profound tumor growth inhibition compared to other HRAS-mutant xenografts, which may be at least in part due to the concomitant PIK3CA mutation and the emergence of early adaptive or acquired resistance." (PMID 35459782, 2022). "We hypothesised that complete loss of PTEN, regardless of PIK3CA mutations, could mediate immune resistance in our cohort through different mechanisms that deserve further investigation, including deep tumour microenvironment analysis." (PMID 36613564, 2022). "In the hormone receptor-negative group (irrespective of HER2 status), patients with PIK3CA-mutated tumours (n = 21 of 188, 11.2%) showed numerically fewer RFI-events (3 of 21 vs 43 of 167) consistent with a higher RFI probability (84.4% and 72.9%, resp.; adjusted HR 0.49, 95% CI 0.152–1.597)." (PMID 36279023, 2022).
tumor (continued). "However, in patients with plasma-negative results, reflexing to tumour tissue testing for the presence of PIK3CA mutations should be performed if possible." (PMID 35055414, 2022). "Interestingly, patients with SHR-negative tumours experienced a better overall survival if a PIK3CA-mutation was detected." (PMID 36279023, 2022). "The patient not achieving pCR had a tumor carrying a double PIK3CA mutation." (PMID 35740668, 2022). "The serum levels of VEGF, IL-8, and IL-10, as well as the expression of RIP2 and PIK3CA in tumor tissues, were highly correlated to clinical features of DLBCL, and high expression level of these indexes may have adverse effects for the prognosis of DLBCL patients." (PMID 36567775, 2022). "Moreover, the drug combination did not induce tumor regression of a CRC patient-derived xenograft (PDX) harboring a PIK3CA H1047R kinase domain mutation." (PMID 35418124, 2022). "Based on the outcomes of the CBYL719 × 2101 trial, alpelisib showed promising results and tolerable toxicity in PIK3CA-mutant tumor patients, demonstrating that isoform-selective PI3K inhibitors combined with other antitumor regimens may be efficient in treating PIK3CA-mutant tumors." (PMID 36539659, 2022). "Comparing somatic mutation rates in SMGs between clusters using binomial regression identified PIK3CA (FDR = 0.001) and EP300 (FDR = 0.046) mutations as disproportionally more common in C1 tumours and STK11 (FDR = 0.005) and NF2 (FDR = 0.045) as enriched in C2 tumours." (PMID 36207323, 2022). "We found that palbociclib plus alpelisib led to the highest degree of synergism in inhibiting tumor cell growth of the three combinations (average ExcessHSA score: − 213.24), with significantly higher ExcessHSA scores observed in PIK3CA mut/amp cell lines than that of PIK3CA WT lines (P = 0.0253)." (PMID 35546399, 2022). "This suggests that excessive tumor-generated HB-EGF might prevent PEPDG278D from binding to EGFR, and also suggests that EGFR signaling remains important to the tumors carrying activating mutations of KRAS, BRAF and/or PIK3CA." (PMID 35650607, 2022). "In total, 11 patients harbored PI3K pathway lesions including two patients for whom pre-treatment tumor tissue sequencing identified PTEN loss-of-function mutations, and nine patients for whom baseline plasma sequencing identified additional PTEN or PIK3CA mutations." (PMID 35304457, 2022). "In the study of The Cancer Genome Atlas Network for HNSCC, the percentages (%) of PTEN genetic alterations in HPV (+) and HPV (-) tumours were 12% and 6%, respectively, and either PTEN mutation or inhibition could result in PIK3CA/CCND1/CDK6 pathway activation and thereby enhance cell proliferation." (PMID 35421166, 2022). "Interestingly, the only patient not achieving pCR had a tumor with two co-occurring PIK3CA mutations." (PMID 35740668, 2022). "Further analysis such as side of tumour (left or right) or evidence of a PIK3CA mutation may be helpful, however this is often not reported." (PMID 36358810, 2022). "Another reason for the low tumor-plasma concordance in our study may be the too low VAF of the mutations identified in tumors for some genes (e.g., MTOR, PIK3CA, ERBB3, and RAF1), raising the question of whether they are driver mutations or just passenger variants." (PMID 34356096, 2021).